IL15 (interleukin 15)
Diseases named in the same sentence as IL15 in open-access papers (continued):
Sharing a sentence is not in itself a finding about the gene and the disease.
HIV-1 infection (continued). "Having found that IL-15 stimulation is able to maximize the functionality of cord blood NK cells for DART molecule-redirected killing has generated another important question: are neonatal NK cells naturally primed by IL-15 in vivo during HIV-1 infection?" (PMID 32373131, 2020). "IL-15 was transiently detected in the plasma during acute HIV-1 infection of adults, with a median time of first detection being 6 days after viremia reached detectable levels in peripheral blood plasma." (PMID 32373131, 2020). "IL-15 has been postulated to play an important role in immunity in HIV-1 infection, but results published so far have been contradictory." (PMID 28904191, 2017). "IL-15 has been proposed to potentially play a role in HIV-1 infection as either a vaccine adjuvant or as a therapeutic cytokine." (PMID 27880829, 2016). "IL-15 has been postulated to play an important role in HIV-1 infection, yet there are conflicting reports regarding its expression levels in these patients." (PMID 27880829, 2016). "IL-15 levels were measured in 501 people (460 patients with HIV-1 infection and 41 uninfected controls)." (PMID 27880829, 2016). "We sought to see if there was a correlation of IL-15 in HIV-1 infection with other markers of monocyte activation, including sCD14 and sCD163 and indeed found that both of these parameters were significantly correlated with IL-15 expression." (PMID 27880829, 2016). "Stimulation of NK cells with a superagonistic IL-15 antibody increased their cytotoxic activity and was able to inhibit acute HIV-1 infection in humanized mice." (PMID 27821119, 2016). "This is the largest study to date looking at the levels of IL-15 in HIV-1 patients stratified according to viral load and correlating this with other important biomarkers associated with HIV-1 infection." (PMID 27880829, 2016). "These increases in IL-15 were closely correlated with markers of inflammation and coagulation and appear to be part of the overall immune activation seen in the context of HIV-1 infection." (PMID 27880829, 2016). "For instance, bystander activation occurs mainly through cytokines, including interferon-α/β, IL-2 and IL-15, which are all increased in HIV-1 infection and represent independent and accurate predictors of disease progression." (PMID 23382678, 2013). "Treatment with IL-15 compensates for the metabolic defects of NK cells in HIV-1 infection." (PMID 38385747, 2024). "IL-15 priming produced similar levels of IFN-γ by NK cells following receptor stimulation, irrespective of HIV-1 status, showing functional restoration of low-level ex vivo IFN-γ responses in HIV-1 infection to levels equivalent to that observed for HIV-1– donors following IL-15 pretreatment." (PMID 38385747, 2024). "Interestingly, the fold change increase in IFN-γ production by NK cells, especially adaptive subsets, was higher in HIV-1 infection following IL-15 pretreatment." (PMID 38385747, 2024). "Importantly, Hu-NSG-Tg(IL-15) mice are susceptible to HIV-1 infection, and their NK cells respond to HIV-1 infection with cytokine production, degranulation, and proliferation." (PMID 36851579, 2023). "Interestingly, IL-15 is currently being evaluated as an immune-modulatory agent in multiple clinical studies designed to increase drug-free control of HIV-1 infection." (PMID 38048223, 2023). "In our study, a decreased plasma level of IL-15 was one of the factors differentiating drug-naïve patients at HIV-1 infection stage 3 coinfected with Mtb from the cases of drug-naïve patients at HIV-1 infection stage 3 and drug-naïve patients with Mtb monoinfection, supporting an earlier study." (PMID 37376629, 2023). "Next, we tested the impact of IL-15 on R5-tropic HIV-1 infection in humanized mice." (PMID 36821374, 2023). "Finally, Hu-NSG-Tg(IL-15) mice sustained HIV-1 infection and replication, which was reciprocated with robust antiviral responses from human NK cells." (PMID 36851579, 2023).
HIV-1 infection (continued). "A number of studies over the years have suggested that IL-15 may also play an important role in patients with HIV-1 infection." (PMID 27880829, 2016). "As expected, stimulation with IL-15 upregulated glycolysis (ECAR), and similarly to observations in HIV-1 infection, there was a decreased OCR/ECAR ratio and reliance on oxidative metabolism." (PMID 38385747, 2024). "In the present study, we aimed to understand the role of IL-15 in the survival and proliferation CCR5+CD4+ T cells prior to and during HIV-1 infection." (PMID 36821374, 2023). "Unsurprisingly, Hu-NSG-Tg(IL-15) mice showed similar increases in IFN-γ and perforin expression, and increased proliferation in circulating NK cells during HIV-1 infection." (PMID 36851579, 2023). "Our observation that γc cytokines, specifically IL-2, IL-7, IL-15, and IL-21 were potent inducers of Tim-3 expression on T cells in the antigen-independent manner in HBV infection were consistent with the role of these cytokines in HIV-1 infection." (PMID 28401068, 2017). "One may speculate that in chronic HIV-1 infection, CD4 and CD8+ T cells that are poorly responsive to normal physiological and homeostatic pathways involving IL-15, may need higher circulating levels of IL-15 to remain functional." (PMID 27880829, 2016). "IL-15, but not IL-7, improved the survival of CCR5+CD4+ T cells, drove their expansion, and facilitated HIV-1 infection in vitro and in humanized mice." (PMID 36821374, 2023). "We have previously shown that short-term IL-15 treatment of HIV-specific CD8+ T cells from noncontrollers increased the capacity of these cells to mobilize mitochondrial activities and suppress HIV-1 infection of CD4+ T cells." (PMID 35380989, 2022). "Interestingly, β.anti-NKG2A without IL-15 (mean 60.7% ± 6.47%) had a similar effect than the other molecules, suggesting that blocking the NKG2A receptor in the context of HIV-1 infection had a more robust effect on degranulation as compared to Raji cells." (PMID 37936122, 2023).
multiple sclerosis (22 papers, 2014 to 2024). A progressive autoimmune disorder affecting the central nervous system resulting in demyelination. "Heightened plasma and CSF IL-15 has also been described in patients suffering from multiple sclerosis: peripheral inflammation would facilitate the expression of chemokines and adhesion molecules on CD4+ T cells, thus allowing their migration into CNS." (PMID 38704619, 2024). "Our results showed that IL-15 levels in the group of patients with newly diagnosed multiple sclerosis were lower than in the group of healthy subjects, which differs from data available in the literature." (PMID 39000506, 2024). "Under conditions of neuroinflammation, IL-15 is mainly secreted by astrocytes but can also be detected on microglia surrounding infiltrating CD8+ T cells in multiple sclerosis lesions." (PMID 37683329, 2023). "In multiple sclerosis, an AD with inflammatory component, IL-15 was reported to potentiate CD8+T cell activity and promote their production of GM-CSF." (PMID 36059463, 2022). "In the current paper, we have shown that IL-15+ γδ T cells are present in human peripheral blood and their percentage is significantly increased in multiple sclerosis patients." (PMID 34575283, 2021). "Of note, IL-15 has also been proposed as local factor in patients with multiple sclerosis (MS) maintaining autoimmune conditions in the CNS." (PMID 26646698, 2015). "Other identified pathways included the pulmonary fibrosis idiopathic signaling pathway in CD4+ T-cells (p = 9.33E − 06), the multiple sclerosis signaling pathway and the IL-15 production pathway in CD8+ T-cells (p = 9.55E − 07 and p = 3.63E − 05, respectively)." (PMID 39407252, 2024). "In multiple sclerosis, the potential pathogenic characteristics of CD4 + CD28− T cells including cytotoxic and proliferation could be augmented by IL-15." (PMID 36320075, 2022). "Previous studies have suggested the importance of IL-15 in multiple sclerosis pathogenesis." (PMID 34575283, 2021). "Interleukin 15 (IL-15) is known to be involved in the pathogenesis of multiple sclerosis (MS)." (PMID 34575283, 2021). "B cells and monocytes seem to be two major sources of IL-15 in multiple sclerosis patients." (PMID 34575283, 2021). "IL-15 can enhance the cytotoxic potential of CD4+ T cells in multiple sclerosis." (PMID 26834537, 2015). "Although increased IL-15 levels in peripheral blood and the CNS play a crucial role in neuro-inflammatory disorders including multiple sclerosis, encephalomyelitis, and intracerebral hemorrhage, this study could not find any increases in this cytokine in delirium." (PMID 35641947, 2022). "Until now, only one work that studied the effect of IL-15 on the migration capacity of the CD4+CD28null T lymphocytes has been published, and in that case, it was made in multiple sclerosis patients." (PMID 34202487, 2021).
systemic lupus erythematosus (22 papers, 2011 to 2025). An autoimmune multi-organ disease typically associated with vasculopathy and autoantibody production. "In general, pathways associated with IL-15 signaling, B-cell receptor signaling, and systemic lupus erythematosus in B-cell signaling were differentially regulated in all the groups." (PMID 39339686, 2024). "IL-15 signaling, B-cell receptor signaling, and systemic lupus erythematosus in B-cell signaling were differentially regulated among all the groups." (PMID 39339686, 2024). "Olfactory transduction was significantly enriched in the high IL15 subgroup, while systemic lupus erythematosus, protein output, and basal transcription factor were significantly enriched in the low IL15 subgroup." (PMID 37228444, 2023). "The highest statistically significant pathways were: IL-15 signaling, B cell receptor signaling, systemic lupus erythematosus in B cell signaling pathway, communication between innate and adaptive immune cells, and melatonin degradation II." (PMID 35163455, 2022). "In particular, the pathways that showed greater significance with a p-value < 0.05 were: IL-15 signaling, B cell receptor signaling, systemic lupus erythematosus in B cell signaling pathway, communication between innate and adaptive immune cells, and melatonin degradation II." (PMID 35163455, 2022). "Overexpression of IL-15 correlated with the development of murine lupus." (PMID 29023581, 2017). "In addition, the DN T cells that massively accumulate in this Fas-defective lupus model were found to permanently down-regulate the receptors for IL-7 and IL-15, probably due to chronic activation in part mediated by commensal antigens, leading to reduced consumption of these cytokines." (PMID 22102903, 2011). "For instance, in systemic lupus erythematosus (SLE), IL15 (interleukin-15) and LGALS9 (galectin-9) were shown as the most useful features in the prediction." (PMID 39897058, 2025). "The maintenance of inflammation in Systemic Lupus Erythematosus (SLE) patients may be aided by increased granzyme B secretion from NK and NKT-like cells in active SLE patients, which is further exacerbated by circulating IL-15." (PMID 36769064, 2023). "Our transcriptome analysis revealed the involvement of interleukin-15 (IL-15), the B cell receptor signal, the communication between innate and adaptive immune cells, and the B cell signaling pathway in systemic lupus erythematosus (SLE)." (PMID 35163455, 2022). "Similarly, the direct comparison of CHIP and non-CHIP samples returned alteration of pathways related to IL-15 signaling, B cells development, and lupus in B cells signaling." (PMID 36437309, 2022). "In patients with systemic lupus erythematosus (SLE), MAIT cells can be activated by IFN-α, IL-15, and IL-12 plus IL-18 in the absence of exogenous antigens." (PMID 29176983, 2017).
atherosclerosis (21 papers, 2014 to 2025). A disease characterized by the build-up of fatty material and calcium deposition in the arterial wall resulting in partial or complete occlusion of the arterial lumen. "IL-15 is an inflammatory cytokine implicated in several cardiovascular diseases, such as myocardial infarction and atherosclerosis." (PMID 37627527, 2023). "A clinical study has shown that IL-15 gene polymorphisms were susceptible biomarkers for development of subclinical atherosclerosis and CAD." (PMID 33520013, 2021). "CT-1 deficiency in advanced atherosclerosis mediated regulation of paracrine factors, such as interleukin (IL)-3, IL-6, IL-9, IL-15, IL-27, CXCL5, MCP-3, MIP-1α and MIP-1β." (PMID 32238841, 2020). "The roles of IL‐15 in hyperlipidaemia and atherosclerosis are controversial, and the underlying mechanism needs to be further explored." (PMID 32406586, 2020). "This retrospective study shows that, in addition to age (prominent factor), levels of IL-15 are associated with IMT in obese patients with NAFLD suggesting a possible role of this cytokine in the atherosclerosis process, although its diagnostic performance is discrete." (PMID 34095164, 2021). "The exact association between IL‐15 and atherosclerosis needs further elucidation." (PMID 32406586, 2020). "Our data confirm and build upon previous observations that IL-15 is expressed within atherosclerotic plaques, that IL-15 promotes plaque development in a mouse model of atherosclerosis, and that polymorphisms in IL15 are associated with subclinical atherosclerosis." (PMID 32976527, 2020). "IL-15 can exacerbate atherosclerosis by promoting cytotoxic capacity, CX3CR1-dependent vascular-homing, and increasing CD2 expression." (PMID 40454002, 2025). "IL-15 is a pro-inflammatory cytokine that is up-regulated in atherosclerosis and myocardial infarction." (PMID 36849967, 2023). "Age and IL-15 levels were both predictors of early atherosclerosis in this population of obese patients with NAFLD, suggesting a possible role of this cytokine in the atherosclerosis process." (PMID 34095164, 2021). "IL‐15, as a pro‐inflammatory cytokine, is up‐regulated in some cardiovascular diseases, such as myocardial infarction and atherosclerosis." (PMID 32406586, 2020). "It has been demonstrated that IL-6 and IL-15, cytokines that are elevated during atherosclerosis, promote the expansion of these cells, consistent with a reduced frequency of CD8 T cells expressing the IL-6 receptor α chain in patients with coronary artery disease." (PMID 40454002, 2025). "Atherosclerosis and thrombosis may be exacerbated by senescent ECs that produce increased levels of IL-1, IL-6, IL-8, IL-15, monocyte chemoattractant protein-1 (MCP-1), TNF, and other mediators." (PMID 36082127, 2022). "Nevertheless, the association between IL-15 and GM-CSF, b FGF, and MCP-1, showed by our results, allows us to hypothesize that these molecules could play a role in a delayed phase of atherosclerosis." (PMID 34095164, 2021). "Il15 has been detected in atherosclerosis plaques as a proinflammatory cytokine and could attenuate SMC proliferation possibly via inhibiting the chemokine receptor CX3CR1." (PMID 34545275, 2021). "IL-15 is upregulated in some CV diseases, such as myocardial infarction, HF and atherosclerosis." (PMID 33520013, 2021). "Finally, we stress that the sensitivity analysis concerning the role of IL-15 in correctly diagnosing the presence of early atherosclerosis resulted in a moderate reliability." (PMID 34095164, 2021). "Whether IL-7 and IL-15 have a role in atherosclerosis is less well established." (PMID 32647892, 2021).
atherosclerosis (continued). "Thus, we have identified a possible feed-forward model of atherosclerosis in which plaque-infiltrating CX3CR1+ CD8 T cells are exposed to vascular EC-derived IL-15 that induces antigen-independent TNF release, resulting in enhanced release of CX3CL1 and IL-15 from ECs." (PMID 32976527, 2020). "First, we identified increased expression of CX3CL1 and IL-15 in the aortic endothelium of monkeys infected with SIV or SHIV and in carotid arteries and plaques of HIV-uninfected persons with atherosclerosis." (PMID 32976527, 2020). "In fact, age and IL-15 levels were both predictors of early atherosclerosis in a population of obese patients with NAFLD, suggesting a possible role of this cytokine in the atherosclerosis process." (PMID 38504163, 2024). "Inflammatory modulators/biomarkers, such as IL-1α, IL-1β, IL-6, IL-12, IL-15, IL-18, and tumor necrosis factor α, or alternative anti-inflammatory cytokine IL-10, and adhesion molecules (ICAM-1, VCAM-1), involved in atherosclerosis progression have been shown to predict cardiovascular diseases." (PMID 37374202, 2023). "In addition, IL-15 was found a regulator of fractalkine (FKN)-CX3CR1 chemokine signaling system, which is involved in the acceleration of atherosclerosis and promoting smooth muscle cell proliferation." (PMID 33520013, 2021). "In this report, we define a novel model of CD8 T cell involvement in atherosclerosis whereby CX3CL1 and IL-15 operate in tandem within the vascular endothelium to promote infiltration by activated CX3CR1+ memory CD8 T cells that drive further endothelial activation via TNF." (PMID 32976527, 2020). "IL‐15 is also involved in the expansion and survival of natural killer T (NKT) cells, which can form an essential link between the innate and adaptive immune responses and enhance atherosclerosis." (PMID 32406586, 2020). "Furthermore, IL15, which mediates its signal through STATs including STAT6, was reduced more during monocyte-to-macrophage differentiation in patients with SLE, especially in those with atherosclerosis." (PMID 25011540, 2014). "We next measured CX3CL1, IL-15, and CD8 T cells in carotid tissues from HIV-uninfected donors with or without atherosclerosis." (PMID 32976527, 2020). "The prediction of IMT by IL-15 coupled with the lack of prediction by the well-known CAD risks is in agreement with recent data, which emphasizes the main role of the immune system in the onset/worsening of atherosclerosis, even though the role of visceral adiposity should be further deepened." (PMID 34095164, 2021).